NOL11 (nucleolar protein 11)
Description:
Ribosome biogenesis factor. May be required for both optimal rDNA transcription and small subunit (SSU) pre-rRNA processing at sites A', A0, 1 and 2b.
Synonyms: DKFZP586L0724
Tractability: PROTAC: ubiquitination databases record sites on it; its protein half-life has been measured.
Gene: Protein-coding gene on chromosome 17 (67,717,812 to 67,744,531, forward strand). Ensembl gene ENSG00000130935.
Subcellular location: Nucleus, nucleolus
Subcellular location (Human Protein Atlas): Nucleoli
Pathways (Reactome):
Metabolism of RNA: Major pathway of rRNA processing in the nucleolus and cytosol; rRNA modification in the nucleus and cytosol
Gene Ontology:
Molecular function: protein binding; RNA binding
Biological process: maturation of SSU-rRNA; positive regulation of transcription of nucleolar large rRNA by RNA polymerase I
Cellular component: nucleolus; t-UTP complex; nucleoplasm; small-subunit processome; nucleus
Genetic constraint (gnomAD): Loss-of-function variants: 18 observed, 33.23 expected, observed/expected ratio (o/e) 0.54, 90% interval 0.37 to 0.8. The upper end of that interval is the gene's LOEUF score, 0.8, which puts it in group 3 of 6, group 1 being the genes least tolerant of losing a copy. Missense variants: 386 observed, 425.31 expected, observed/expected ratio (o/e) 0.91, 90% interval 0.83 to 0.99. Synonymous variants: 138 observed, 153.44 expected, observed/expected ratio (o/e) 0.9, 90% interval 0.78 to 1.04.
Homologues: Orthologues: chimpanzee NOL11 (99% identical), macaque NOL11 (97% identical), dog NOL11 (85% identical), pig NOL11 (83% identical), rabbit NOL11 (83% identical), guinea pig NOL11 (81% identical), mouse Nol11 (76% identical), rat Nol11 (76% identical), tropical clawed frog nol11 (42% identical), zebrafish nol11 (37% identical), Drosophila melanogaster CG9300 (16% identical).
Diseases named in the same sentence as NOL11 in open-access papers:
NOL11 is named in the same sentence as 13 diseases in open-access papers, as found by Europe PMC text mining. Sharing a sentence is not in itself a finding about the gene and the disease. The quoted sentences say what the papers report.
biliary cirrhosis (1 paper, 2025). "Mutations in the ribosome assembly factors hUTP4 (human U three protein 4)/Cirhin and NOL11 (nucleolar protein 11), responsible for synthesizing 18S rRNA, have been found to cause biliary cirrhosis in North American Indian children." (PMID 40521004, 2025).
microcephaly (1 paper, 2015). A congenital or acquired developmental disorder in which the circumference of the head is smaller than normal for the person's age and sex. "Knockdown of nol11 resulted in microcephaly and pronounced defects in CNC derived craniofacial cartilages in 86% (n = 389) of treated embryos, while control MO (CMO) injected embryos were unaltered." (PMID 25756904, 2015).
virus infection (1 paper, 2020). "The relationship between virus infection and NOL11 have not been reported, however, it is localized to the nucleolus and required for pre-rRNA transcription." (PMID 32056668, 2020).
NOL11 also shares sentences with these, for which no sentence is quoted: breast carcinoma (1 paper); cancer (1); Cirrhosis (1); lung carcinoma (1); migraine (1); ovarian carcinoma (1); prostate carcinoma (1); renal cell cancer (1); Sepsis (1); Treacher-Collins syndrome (1).